MDM2 (MDM2 proto-oncogene)
Diseases named in the same sentence as MDM2 in open-access papers (continued):
Sharing a sentence is not in itself a finding about the gene and the disease.
acute myeloid leukemia (76 papers, 2007 to 2026). Acute myeloid leukemia (AML) is a group of neoplasms arising from precursor cells committed to the myeloid cell-line differentiation. "In hematological malignancies, the MDM2 SNP309 G-allele is associated with increased risk for acute myeloid leukemia (AML) and chronic myelogenous leukemia (CML)." (PMID 26416416, 2015). "RG7112 is a Nutlin analog with higher specificity for MDM2 and can induce more robust apoptosis of acute myeloid leukemia (AML) and chronic lymphocytic leukemia (CLL) cells than Nutlin 3a." (PMID 37509223, 2023). "Prior studies examining venetoclax in combination with MDM2 inhibition in the context of acute myeloid leukemia have shown promising results." (PMID 37838759, 2023). "For reasons that are not fully understood, MDM2 inhibition has been more successful in other malignancies such as acute myelogenous leukemia, chronic lymphocytic leukemia, and multiple myeloma, in which early-phase clinical trials have demonstrated efficacy." (PMID 36439412, 2022). "Studies suggest that MDM2 is overexpressed in multiple human cancers, including breast cancer (15%), glioblastoma (14%), sarcomas (20%), and acute myeloid leukemia (AML), and has been shown to promote metastasis in some cancers." (PMID 33924734, 2021). "KRT-232 (Kartos, Redwood City, CA, USA) is a potent oral MDM2 inhibitor currently in clinical development for the treatment of MF and acute myeloid leukemia (AML)." (PMID 33925695, 2021). "A previous gene expression study on three patients with acute myeloid leukemia used the same time intervals between biopsies that we used, and they found MDM2 upregulation." (PMID 28052121, 2017). "Venetoclax, a small molecule BH3 mimetic which inhibits the anti-apoptotic protein Bcl-2, and idasanutlin, a selective MDM2 antagonist, have both shown activity as single-agent treatments in pre-clinical and clinical studies in acute myeloid leukemia (AML)." (PMID 27353420, 2016). "For example, MDM2 overexpression is known to be predictive of sensitivity to Nutlin-3 in acute myeloid leukemia and acute lymphoblastic leukemia." (PMID 26274927, 2015). "The simultaneous blockade of MEK and MDM2 induces apoptosis in acute myeloid leukemia, indicating the therapeutic potential of this combination." (PMID 25537510, 2015). "Several MDM2 inhibitors are in clinical trials for acute myeloid leukemia (AML) treatment." (PMID 38265263, 2024). "This phase 1 study assessed the safety and efficacy of different dosing regimens of the MDM2 inhibitor milademetan as monotherapy and in combination with azacitidine (AZA) in patients with relapsed or refractory acute myeloid leukemia or high‐risk myelodysplastic syndromes." (PMID 39030997, 2024). "Idasanutlin (RG7388) with more potency, selectivity, and better pharmacokinetic profile than other MDM2 inhibitors appears interesting in preclinical assays, is tested in clinical trials for acute myeloid leukemia and recently in the N2M2 (NOA-20) clinical trials in GBM (NCT01358389)." (PMID 33918704, 2021).
acute myeloid leukemia (continued). "Clinical trials on MDM2 inhibitors are ongoing in acute myeloid leukemia (AML) (NCT02319369, NCT03634228), soft tissue sarcoma (NCT03217266), malignant salivary gland carcinoma (NCT03781986), pediatric cancers (NCT03654716) and small cell lung cancer (NCT04022876)." (PMID 34307171, 2021). "Acute Myeloid Leukemia (AML): With an increased efficacy, Idasanutlin, as of 2018, is the only MDM2 antagonist that has entered phase III clinical trials." (PMID 35563397, 2022). "Amplification and overexpression of the myeloid cell leukemia differentiation protein MCL1 and the murine double minute protein MDM2 have been reported in various human tumors as well as hematological malignancies including acute myeloid leukemia (AML)." (PMID 31718075, 2019). "Idasanutlin is a potent and selective small-molecule MDM2 (murine double minute 2) antagonist in phase 3 clinical trial for refractory/relapsed acute myeloid leukemia (AML)." (PMID 30511219, 2019). "Notably, the FDA recently granted orphan drug designation to KT-253, a novel MDM2 degrader, for the treatment of acute myeloid leukemia (AML), underscoring the clinical potential of this innovative strategy." (PMID 41170373, 2025). "CTX1 alone or in combination with an MDM2 inhibitor nutlin-3 has been found to induce cancer cell growth arrest and apoptosis in vitro and extend the survival of mice bearing acute myeloid leukemia (AML) xenograft tumors in vivo." (PMID 32850448, 2020). "A clinical phase III trial using MDM2/X inhibitors, idasanutlin (RG7388) combined with cytarabine, is being performed involving relapse/refractory acute myeloid leukemia patients." (PMID 31689961, 2019).
acute myeloid leukemia (continued). "Fluorescent lanthanide oxyfluoride nanoparticles conjugated with anti-CD-33 antibody for potential treatment of acute myeloid leukemia by conjugating PMI, a dodecameric peptide antagonist of MDM2 and MDMX and a CD-33-targeted humanized monoclonal antibody to nanoparticles via metal thiolate bonds." (PMID 38334567, 2024). "Regarding MDM2/X inhibitors, a clinical phase III trial using combination with idasanutlin (RG7388) and cytarabine, which is a chemotherapeutic agent, is being performed in relapse/refractory acute myeloid leukemia patients." (PMID 31689961, 2019). "We investigated the correlation between cell sensitivity to apoptogenic agents and mitochondrial profiling, using a panel of acute myeloid leukemias induced to undergo apoptosis by exposure to cytarabine, the BH3 mimetic ABT-199, the MDM2 inhibitor Nutlin-3a, or the CRM1 inhibitor KPT-330." (PMID 26375587, 2015). "Amongst the increasing number of MDM2 antagonists entering clinical investigation in recent years, idasanutlin has progressed furthest with its use in the phase 3 MIRROS trial (NCT02545283) in combination with cytarabine for the treatment of relapsed or refractory acute myeloid leukemia (AML)." (PMID 38600316, 2024). "In a current phase-I dose-escalation study, an MDM2 antagonist (RO6839921) is intravenously applied in patients with advanced malignancies, including acute myeloid leukemia (AML) (NCT02098967)." (PMID 29794999, 2018). "In acute myeloid leukemia, a combined MEK/MDM2 blockade may induce apoptosis." (PMID 25537510, 2015). "Unfortunately, in a completed Phase III clinical trial (NCT02545283), the combination of the MDM2 inhibitor idasanutlin (RG-7388) and cytarabine did not improve overall survival in patients with relapsed or refractory acute myeloid leukemia (AML)." (PMID 39223632, 2024). "This study found that FGNs could treat acute myeloid leukemia subtype 2 (AML-M2) by silencing five essential oncogenes (BAG1, MDM2, Bcl-2, BIRC5, and XIAP) in AML-M2." (PMID 36612296, 2023).
ovarian carcinoma (69 papers, 1995 to 2025). A malignant neoplasm originating from the surface ovarian epithelium. "In the present study, we explored the impact of a third MDM2 polymorphism, del1518 ins/del, located in promoter P1, on the risk of endometrial and ovarian cancer in a Caucasian population." (PMID 28158999, 2017). "A meta-analysis was performed to examine the association between MDM2 309T>G polymorphism and ovarian cancer risk." (PMID 23383041, 2013). "As ovarian cancer is largely hormone related, it is important to study the impact of MDM2 309 polymorphism on women with ovarian cancer." (PMID 23383041, 2013). "Over the last two decades, a number of case–control studies were conducted to investigate the association between MDM2 polymorphism and ovarian cancer risk in humans." (PMID 23383041, 2013). "Recently, there have been a number of studies on the association between MDM2 (Murine Double Minute 2) 309 polymorphism and ovarian cancer risk." (PMID 23383041, 2013). "A commonly occurring T-to-G polymorphism at nucleotide 309 (T309G) of MDM2 has been the focus of many case-control association studies of ovarian cancer in different ethnic populations." (PMID 23383041, 2013). "Here, we report an elevated OR for ovarian cancer in BRCA1 mutation carriers harboring a MDM2 SNP309TG or SNP309GG genotype." (PMID 23039163, 2012). "We further examined the effect of MDM2 SNP status with respect to age at onset of ovarian cancer in BRCA mutation carriers." (PMID 23039163, 2012). "In order to evaluate the potential impact of MDM2 del1518 status on endometrial and ovarian cancer risk, we evaluated the OR by comparing the frequency of the MDM2 del1518 genotypes observed in ovarian and endometrial cancer cases to the SNP status among the 1,872 healthy female controls." (PMID 28158999, 2017). "SNP285C reduces the binding strength between the Sp1 transcription factor and the MDM2 promoter, and is associated with a significantly reduced risk of spontaneous breast, endometrial and ovarian cancer as well as a reduced risk of ovarian cancer among BRCA1 mutation carriers." (PMID 25327560, 2014). "This meta-analysis provides evidence of the association between MDM2 309 polymorphism and ovarian cancer risk, supporting the hypothesis that MDM2 SNP309 G allele probably acts as an important ovarian cancer protective factor in Asians, but not in Caucasians." (PMID 23383041, 2013). "Thus, we performed a meta-analysis to explore more precisely the association between MDM2 309 polymorphism and the risk of ovarian cancer." (PMID 23383041, 2013). "However, the combination of both SNPs into a commonly observed haplotype reduces SP1 binding in the MDM2 promoter and reduces breast and ovarian cancer risk, likely by reducing MDM2 expression." (PMID 22950704, 2012). "In this meta-analysis, after a critical review of the 6 studies on MDM2 SNP309 polymorphism (a total of 1534 cases and 2211 controls), a comprehensive assessment was performed to investigate whether polymorphisms in MDM2 SNP309 was significantly associated with risk of ovarian cancer." (PMID 23383041, 2013). "MDM2, a novel non‐histone substrate of hMOF, directly interacts with hMOF, leading to MDM2 acetylation, which inhibits its ubiquitination and degradation, thereby increasing MDM2 stability and enhancing cisplatin resistance in ovarian cancer cells." (PMID 39778006, 2025).